TWSG1 (twisted gastrulation BMP signaling modulator 1)
Description:
May be involved in dorsoventral axis formation. Seems to antagonize BMP signaling by forming ternary complexes with CHRD and BMPs, thereby preventing BMPs from binding to their receptors. In addition to the anti-BMP function, also has pro-BMP activity, partly mediated by cleavage and degradation of CHRD, which releases BMPs from ternary complexes. May be an important modulator of BMP-regulated cartilage development and chondrocyte differentiation. May play a role in thymocyte development (By similarity).
Synonyms: TSG
Tractability: Antibody: UniProt places it where antibodies can reach, with medium confidence; UniProt predicts a signal peptide or a membrane-spanning region; its Gene Ontology location is reachable by antibodies, with medium confidence. PROTAC: ubiquitination databases record sites on it.
Gene: Protein-coding gene on chromosome 18 (9,334,694 to 9,402,420, forward strand). Ensembl gene ENSG00000128791.
Subcellular location: Secreted
Subcellular location (Human Protein Atlas): Centrosome; Cytosol; Predicted to be secreted
Gene Ontology:
Molecular function: protein binding; transforming growth factor beta binding; heparin binding
Biological process: negative regulation of CD4-positive, alpha-beta T cell activation; negative regulation of CD4-positive, alpha-beta T cell proliferation; negative regulation of cytokine production; positive regulation of SMAD protein signal transduction; positive regulation of transforming growth factor beta receptor signaling pathway; regulation of BMP signaling pathway
Cellular component: centrosome; cytosol; extracellular region
Genetic constraint (gnomAD): Loss-of-function variants: 14 observed, 22.74 expected, observed/expected ratio (o/e) 0.62, 90% interval 0.41 to 0.96. The upper end of that interval is the gene's LOEUF score, 0.96, which puts it in group 4 of 6, group 1 being the genes least tolerant of losing a copy. Missense variants: 240 observed, 288.86 expected, observed/expected ratio (o/e) 0.83, 90% interval 0.75 to 0.93. Synonymous variants: 86 observed, 97.67 expected, observed/expected ratio (o/e) 0.88, 90% interval 0.74 to 1.05.
Homologues: Orthologues: chimpanzee TWSG1 (99% identical), macaque TWSG1 (99% identical), guinea pig TWSG1 (96% identical), pig TWSG1 (95% identical), rat Twsg1 (93% identical), mouse Twsg1 (93% identical), dog TWSG1 (92% identical), rabbit TWSG1 (82% identical), tropical clawed frog twsg1 (77% identical), zebrafish twsg1a (70% identical), Drosophila melanogaster cv (36% identical), Drosophila melanogaster tsg (34% identical), and 1 more.
Diseases named in the same sentence as TWSG1 in open-access papers:
TWSG1 is named in the same sentence as 27 diseases in open-access papers, as found by Europe PMC text mining. Sharing a sentence is not in itself a finding about the gene and the disease. The quoted sentences say what the papers report.
holoprosencephaly (3 papers, 2007 to 2022). Holoprosencephaly (HPE) is a complex brain malformation resulting from incomplete cleavage of the prosencephalon, occurring between the 18th and 28th day of gestation, and affecting both the forebrain and face, which results in neurological manifestations and facial anomalies of variable severity. "All Twsg1 mutant mice, irrespective of genetic background, exhibit deletions of neural arches in the cervical vertebrae, and C57BL/6 ones present pronounced forebrain defects including rostral truncations, holoprosencephaly, cyclopia, agnathia." (PMID 17274816, 2007).
anaemia (2 papers, 2017 to 2022). "No changes in total Twsg1 gene expression were observed in any of the genetic models of anemia, but interestingly expression levels per erythroid cell decreased in both the bone marrow and spleen of Hbbth3/+ and hbd mice." (PMID 28135344, 2017).
thalassemia (2 papers, 2009 to 2019). An inherited blood disorder characterized by a decreased synthesis of one of the polypeptide chains that form hemoglobin. "In thalassemia, over-expression of TWSG1 would inhibit the host’s ability to sense and respond to iron loading." (PMID 21415988, 2009). "It is also hypothesised that the increased expression of TWSG1 may also impact erythropoiesis in thalassemia by inhibiting the BMP4 dependent expansion of stress erythroblasts, which in turn would exacerbate the anemia." (PMID 21415988, 2009). "In thalassemia, ineffective erythropoiesis induces the release of factors including GDF15, twisted gastrulation protein homolog 1 (TWSG1), hypoxia-inducible factor (HIF), and ERFE, which can all inhibit hepcidin release." (PMID 30834265, 2019). "It is proposed that TWSG1 and GDF15 act together to inappropriately inhibit hepcidin expression in thalassemia." (PMID 21415988, 2009).
cholangiocellular carcinoma (1 paper, 2022). "TWSG1 expression is upregulated in cholangiocellular carcinoma, hepatocellular carcinoma, papillary thyroid cancer (PTC), and glioblastoma but downregulated in gastric and endometrial cancers." (PMID 36361543, 2022). "Furthermore, TWSG1 is highly expressed in cholangiocellular and hepatocellular carcinoma, and interestingly, immunohistochemistry and immunoblotting showed a stronger TWSG1 expression in cholangiocellular carcinoma than in hepatocellular carcinoma." (PMID 36361543, 2022). "In addition, a striking correlation between TWSG1 and BMP4 expression was found in cholangiocellular carcinoma, which raises questions about the possible role of TWSG1 in modulating invasive behavior or initiating the process of lymphovascular invasion." (PMID 36361543, 2022).
colorectal cancer (1 paper, 2022). A primary or metastatic malignant neoplasm that affects the colon or rectum. "A loss of heterozygosity and truncating variants of TWSG1 have been observed in familial colorectal cancer." (PMID 36361543, 2022).
endometrial cancer (1 paper, 2022). Primary or metastatic malignant neoplasm involving the endometrium (mucous membrane that lines the endometrial cavity). "TWSG1 expression was upregulated in papillary thyroid carcinoma and glioblastoma but downregulated in gastric and endometrial cancers." (PMID 36361543, 2022). "In contrast, TWSG1 suppresses BMP7-enhanced sphere formation and migration in endometrial cancer cells, indicating the tumor-suppressive role of TWSG1 in endometrial cancer." (PMID 36361543, 2022). "TWSG1 suppressed BMP7-enhanced sphere formation and migration in endometrial cancer cells, indicating its tumor-suppressive role." (PMID 36361543, 2022).
gastric cancer (1 paper, 2022). A primary or metastatic malignant neoplasm involving the stomach. "In gastric cancer, TWSG1 expression was low, and the lower expression level showed a correlation with higher pathological grading or the clinical stage of patients." (PMID 36361543, 2022). "Thus, it is possible that TWSG1 acts as a tumor suppressor gene in gastric cancer." (PMID 36361543, 2022).
glioblastoma (1 paper, 2022). The most malignant astrocytic tumor (WHO grade IV). "TWSG1 also positively modulates glioblastoma cell growth in vitro and in vivo." (PMID 36361543, 2022).
Hydrocephalus (1 paper, 2022). Hydrocephalus is an active distension of the ventricular system of the brain resulting from inadequate passage of CSF from its point of production within the cerebral ventricles to its point of absorption into the systemic circulation. "In addition, TWSG1-null mice have shown a higher frequency of hydrocephalus than wild-type mice, suggesting a neuroprotective function of TWSG1." (PMID 36361543, 2022).
hyperlipidemia (1 paper, 2014). "Twsg1 null mice exhibited milder hypoalbuminemia and hyperlipidemia, and milder histological changes while maintaining the expression of podocyte markers during podocyte injury model." (PMID 24586548, 2014). "While Twsg1+/+:NEP25 mice exhibited severe nephrotic syndrome characterized by massive proteinuria, hypoalbuminemia and hyperlipidemia, Twsg1LacZ/LacZ:NEP25 mice showed milder hypoalbuminuria and hyperlipidemia." (PMID 24586548, 2014).
malignant mesothelioma (1 paper, 2022). A malignant neoplasm of the pleura or peritoneum, arising from mesothelial cells. "Therefore, TWSG1 may influence cancer stemness in malignant mesothelioma." (PMID 36361543, 2022). "Furthermore, TWSG1 expression is downregulated by promoter methylation in human malignant mesothelioma side-population (SP) cells compared to non-SP cells." (PMID 36361543, 2022).
osteoporosis (1 paper, 2022). A condition of reduced bone mass, with decreased cortical thickness and a decrease in the number and size of the trabeculae of cancellous bone (but normal chemical composition), resulting in increased fracture incidence. "In fact, TWSG1-null mice exhibit mild vertebral abnormalities and osteoporosis." (PMID 36361543, 2022).
prostate carcinoma (1 paper, 2023). A carcinoma that arises from epithelial cells of the prostate gland. "Soluble antagonists to BMP signaling were also unremarkable in comparison to lytic‐ or blastic‐like tumor induced bone disease phenotype prostate cancer cell lines, with only TWSG1 having slight elevation in lytic‐like cells." (PMID 36054271, 2023).
cancer (4 papers, 2013 to 2025). A tumor composed of atypical neoplastic, often pleomorphic cells that invade other tissues. "In papillary thyroid cancer, TWSG1 knockdown inhibited migration, invasion, and proliferation, suggesting a role in enhancing cancer cell functionality." (PMID 40212011, 2025). "Further studies are required to clarify the TWSG1 function and its association with BMP signaling in cancer development." (PMID 36361543, 2022). "Further studies are needed to clarify the function of TWSG1 and its association with BMP signaling in cancer development." (PMID 36361543, 2022). "In conclusion, TWSG1 has a variety of functions ranging from fertility to cancer in multiple organs." (PMID 36361543, 2022). "These proteins, such as Twisted gastrulation protein‐1 (Twsg1, encoded by TWSG1) and Crossveinless (CV), enhance BMP inhibition and may promote cancer formation." (PMID 40212011, 2025). "Although further studies are needed to clarify these mechanisms, the modulation of TWSG1 signaling could be promising for treating specific diseases and cancers." (PMID 36361543, 2022). "The relationship between TWSG1 expression and cancer development has also been elucidated." (PMID 36361543, 2022). "TWSG1 has various functions ranging from embryogenesis to cancer progression." (PMID 36361543, 2022). "In this review, we focus on TWSG1 biology ranging from embryogenesis to cancer development." (PMID 36361543, 2022). "Thus, TWSG1 has various functions ranging from fertility to cancer." (PMID 36361543, 2022). "Furthermore, the relationship between TWSG1 and cancer has been elucidated." (PMID 36361543, 2022). "Therefore, TWSG1 signaling modulation may be beneficial in treating specific diseases such as cancer." (PMID 36361543, 2022). "TWSG1 binds BMPs and their antagonist Chordin to control BMP signaling during embryonic development, kidney regeneration and cancer." (PMID 38862520, 2024). "The following genes displayed LOH in at least one cancer: UACA, TWSG1, PSPH, and ZNF490." (PMID 24146633, 2013).
tumor (4 papers, 2013 to 2023). "Loss of the remaining normal TWSG1 allele was observed in both tumors indicating that the gene might act as a classical tumor suppressor gene." (PMID 24146633, 2013). "We also showed that both the BMP type I receptor kinase inhibitor LDN193189 and TWSG1 have tumor suppressing effects via inhibition of BMP signaling." (PMID 34360647, 2021). "The TWSG1 mRNA expression in EC was found to be significantly lower than in normal endometrium, consistent with a tumor suppressive role of TWSG1 in EC." (PMID 34360647, 2021). "In this study, we demonstrate that BMP signaling has tumor promoting effects on EC, and that both LDN193189, a BMP type I receptor kinase inhibitor, and to some extent TWSG1, reverse these effects on EC cells." (PMID 34360647, 2021).
kidney disease (1 paper, 2014). "Previously we have shown that Twsg1 is the second most abundant Bmp antagonist in the kidney next to USAG-1; nevertheless, the function of Twsg1 during kidney disease progression remains to be elucidated." (PMID 24586548, 2014).
TWSG1 also shares sentences with these, for which no sentence is quoted: Atrophy (1 paper); Autoimmunity (1); embryonic carcinoma (1); glioma (1); hepatocellular carcinoma (1); Hypoalbuminemia (1); nephrotic syndrome (1); papillary thyroid carcinoma (1); rectum adenocarcinoma (1); renal fibrosis (1); thyroid disease (1).